TCF12 (transcription factor 12)
Diseases named in the same sentence as TCF12 in open-access papers (continued):
Sharing a sentence is not in itself a finding about the gene and the disease.
glioblastoma (4 papers, 2021 to 2025). The most malignant astrocytic tumor (WHO grade IV). "Moreover, several Tcf12 rats developed tumors similar to glioblastomas." (PMID 33466745, 2021). "To verify the impact of three genes on the prognosis of glioblastoma patients, we analyzed the TCGA-GBM database and found that high expression of LITAF and OSMR significantly shortened patient overall survival, while high expression of TCF12 significantly extended patient overall survival." (PMID 40859405, 2025).
Anosmia (3 papers, 2023 to 2025). An inability to perceive odors. "Although recent studies identified rare nucleotide substitutions and indels of TCF12 in a few families with CHH and additional clinical features, the significance of TCF12 variants as the cause of Kallmann syndrome remains uncertain." (PMID 40642286, 2025). "Since our patient carried no pathogenic variants in other known CHH-causative genes, monoallelic TCF12 variants appear to be sufficient to cause Kallmann syndrome as a Mendelian disorder." (PMID 40642286, 2025). "The present study provides evidence that heterozygous loss-of-function variants of TCF12 are causes of isolated Kallmann syndrome." (PMID 40642286, 2025). "More importantly, this study argues for the etiological relationship between TCF12 variants and isolated Kallmann syndrome." (PMID 40642286, 2025). "The underlying mechanisms of Kallmann syndrome in TCF12-mutation-positive patients need to be clarified in future studies." (PMID 40642286, 2025). "Here, we report a boy with a novel de novo splice site variant of TCF12 and isolated Kallmann syndrome." (PMID 40642286, 2025). "We identified a hitherto unreported de novo TCF12 variant in a boy with Kallmann syndrome." (PMID 40642286, 2025). "Here we reported an adolescent girl with a similar phenotype (HH and anosmia) who had TCF12 deletion, and she was also diagnosed with papillary thyroid carcinoma." (PMID 39036055, 2024). "We identified a novel de novo splice site variant of TCF12 in a boy with Kallmann syndrome without other clinical features." (PMID 40642286, 2025). "We additionally found that hypogonadotropic hypogonadism-26 with or without anosmia (HH26) was caused by heterozygous or homozygous mutation in TCF12 (600480) on chromosome 15q21." (PMID 37239376, 2023). "However, there are no further reports of TCF12 variants in patients with Kallmann syndrome." (PMID 40642286, 2025).
atherosclerosis (3 papers, 2019 to 2023). A disease characterized by the build-up of fatty material and calcium deposition in the arterial wall resulting in partial or complete occlusion of the arterial lumen. "The results showed that TCF12 played complicated roles in atherosclerosis." (PMID 31354385, 2019).
osteosarcoma (3 papers, 2019 to 2025). A usually aggressive malignant bone-forming mesenchymal neoplasm, predominantly affecting adolescents and young adults. "Recent studies have discovered that TCF12 is involved in tumorigenesis, such as inducing ferroptosis in oral squamous cell carcinoma and promoting angiogenesis in osteosarcoma; however, its role in cardiovascular diseases has been less explored." (PMID 40166462, 2025). "Additionally, TCF12 has been shown to induce angiogenesis in osteosarcoma." (PMID 40166462, 2025).
ovarian carcinoma (3 papers, 2020 to 2024). A malignant neoplasm originating from the surface ovarian epithelium. "For example, TCF12 is a direct target of miR-26a, which has been shown to inhibit the growth of epithelial ovarian cancer (OC) and induce apoptosis by inhibiting the TCF12 expression." (PMID 33413401, 2021). "For example, downregulation of TCF12 dampens the growth, migration and invasion of ovarian cancer and promotes apoptosis." (PMID 33413401, 2021).
thyroid cancer (3 papers, 2014 to 2024). "We could not perform molecular testing or a functional study on the thyroid tissue specimen for the biological function of TCF12 in thyroid carcinoma cells." (PMID 39036055, 2024). "By contrast, somatic mutations of TCF12, KDM5C, IGF2BP3 and MAP4K3 have not been reported in any types of thyroid cancers." (PMID 27626165, 2016).
adenoma (2 papers, 2011 to 2025). A neoplasm arising from the epithelium. "Among these, we identified Tcf12 (transcription factor 12), Plagl1 (pleomorphic adenoma gene-like 1), and other transcription factors that exhibited decreased activity levels with cardiac maturation." (PMID 39960664, 2025). "For qRT-PCR validation of the shift in TCF12 TSS usage, six normal samples, 14 adenoma samples, divided in two groups based on expression of the short TCF12 isoform (high or low), and six MSS cancer samples were selected." (PMID 21999571, 2011). "This indicated that the short isoform of TCF12 was de novo synthesized in the majority of the tumor samples, especially in adenomas and MSS carcinomas." (PMID 21999571, 2011).
brain glioma (2 papers, 2011 to 2020). A malignant glioma that involves the brain. "Isoform expression changes were also found for TCF12 in brain gliomas." (PMID 21999571, 2011).
cervical cancer (2 papers, 2021 to 2022). A primary or metastatic malignant neoplasm involving the cervix. "For example, circ_0000388 works as a ceRNA of miR-337-3p to modulate transcription factor 12 (TCF12) expression and promote the progression of cervical cancer." (PMID 34787066, 2022).
chondrosarcoma (2 papers, 2009 to 2020). A malignant cartilaginous matrix-producing mesenchymal neoplasm arising from the bone and soft tissue. "TCF3 is translocated to a number of fusion partners in pre- and pro-B-ALL, while TCF12 is fused to NR4A3 in extraskeletal mixoid chondrosarcoma." (PMID 19461887, 2009). "The same holds true for rearrangements involving NR4A3 in extraskeletal myxoid chondrosarcomas: while the AMP-FPS assay covers the most NR4A3 common partners (EWSR1, TAF15, TCF12, TFG) it lacks probes for both NR4A3 and uncommon partners, thus scoring negative in the presence of alternative fusions." (PMID 32351889, 2020).
colon cancer (2 papers, 2021 to 2022). "As a target of miR-221, TCF12 has been related to survival after diagnosis of colon cancer, and there is evidence to suggest that TCF12 is involved in cell migration and differentiation." (PMID 33440913, 2021). "Transcriptome analysis of 57 advanced colon cancer samples revealed that one of the non-T cell inflamed subtypes (group 4) had low expression of CD8a, IFNG and GZMB with high expression of SCD1 and CTNNB1(β-catenin) and its downstream molecules including VEGFA and TCF12." (PMID 35793868, 2022).
Coronal craniosynostosis (2 papers, 2016 to 2022). Premature closure of the coronal suture of skull. "In addition, mutations in TCF12 are frequent causes of coronal craniosynostosis, which may severely influence the development and function of the brain." (PMID 27218255, 2016).
developmental delay (2 papers, 2015 to 2024). "In the original series, 14% of patients with a mutation in TCF12 had significant developmental delay or learning disability." (PMID 25871887, 2015).
endometrial cancer (2 papers, 2011 to 2020). Primary or metastatic malignant neoplasm involving the endometrium (mucous membrane that lines the endometrial cavity). "In a mouse experiment, TCF12 was associated with obesity, a key prognostic factor for endometrial cancer." (PMID 21226949, 2011). "In mouse experiments, TCF12 was also identified as a key prognostic factor for endometrial cancer." (PMID 32120995, 2020).
oral carcinoma (2 papers, 2020 to 2021). "miR-211 enhances the oncogenesis of carcinogen-induced oral carcinoma by increasing antioxidant activity and downregulating TCF12." (PMID 33536579, 2021). "MicroRNA-211 enhances the oncogenicity of carcinogen-induced oral carcinoma by repressing TCF12 and increasing antioxidant activity." (PMID 32158692, 2020).
osteoporosis (2 papers, 2023 to 2024). A condition of reduced bone mass, with decreased cortical thickness and a decrease in the number and size of the trabeculae of cancellous bone (but normal chemical composition), resulting in increased fracture incidence. "The shared presence of CEBPB, CTCF, and TCF12 in the regulatory networks of both BRP and OSP genes suggests their potential involvement in the underlying mechanisms of both bone regeneration and osteoporosis." (PMID 37875547, 2023). "The shared TFs CEBPB, CTCF, and TCF12 in the OSP and BRP genes indicate their potential dual role in bone formation and remodeling, suggesting their involvement in osteoporosis." (PMID 37875547, 2023). "In our patient, mild height loss of the vertebral bodies was improved after one year of sex steroid replacement therapy, therefore osteoporosis might not be a direct consequence of TCF12 haploinsufficiency." (PMID 39036055, 2024).
acute lymphocytic leukemia (1 paper, 2016). "SH2B3 (regulates integrin signaling in endothelial cells) and TCF12 (control of lymphoid differentiation) have been linked to acute lymphocytic leukemia." (PMID 27959900, 2016).
anaplastic astrocytoma (1 paper, 2020). "The H3/IDH-wildtype anaplastic astrocytoma harbored I596T and E610K double mutations (in cis) in TCF12, identified by WGS, WES, and RNA-seq." (PMID 32326973, 2020).
CHARGE syndrome (1 paper, 2021). CHARGE syndrome is a multiple congenital anomaly syndrome characterized by the variable combination of multiple anomalies, mainly Coloboma; Choanal atresia/stenosis; Cranial nerve dysfunction; Characteristic ear anomalies (known as the major 4 C's). "Underlying syndromic diagnosis was Crouzon in 35%, followed by Apert (27%), Pfeiffer (10%), Muenke (9%), Saethre-Chotzen (6%), TCF-12 (5%), ERF (3%), and 1 case each of Noonan, Smith Lemil Opitz, craniofrontonasal dysplasia, William, Bartter, Shprintzen-Goldberg, and CHARGE syndrome." (PMID 34554301, 2021).
co-infection (1 paper, 2014). "maxima co-infection compared with uninfected controls (ANXA1, HSP90B1, VEGFA, MTTP, TNFSF11B, TCF12, APP, and CXCL14)." (PMID 25504150, 2014).
colorectal tumors (1 paper, 2011). "A TCF12 short variant was found to be de novo synthesized in colorectal tumors, and TCF12 protein level was shown to be associated with progression free survival, further underlining the potential importance of alternative TSS usage in cancer development." (PMID 21999571, 2011). "Protein levels of OSBPL1A and TCF12 were found to be deregulated in colorectal tumors and the protein expression of TCF12 correlated with progression free survival of stage II CRC." (PMID 21999571, 2011).
diffuse intrinsic pontine glioma (1 paper, 2022). A neuroglial tumor that arises from the middle portion of the brain stem. "In diffuse intrinsic pontine glioma (DIPG), CNV affecting tumor-specific gene expression of TCF12 and amplification of its enhancer have been observed in Hi-C studies." (PMID 35902807, 2022).
dyslexia (1 paper, 2020). A learning disorder characterized by an impairment in processing written words. "TCF12 is coded by the DYX1 locus, associated with inherited dyslexia and neurodevelopmental defects." (PMID 32351715, 2020). "We have also been able to indicate a link connecting inherited dyslexia to neuronal differentiation through TCF12." (PMID 32351715, 2020). "The TCF12 gene is coded by the DYX1 locus, and has been associated with inherited dyslexia and neurodevelopmental defects." (PMID 32351715, 2020). "The third component of the complex is TCF12, a protein coded by the DYX1 locus replicated in several studies in inherited dyslexia." (PMID 32351715, 2020).
endometriosis (1 paper, 2025). The growth of functional endometrial tissue in anatomic sites outside the uterine body. "The results indicated that 13 TFs were identified in both SLE and endometriosis, and 6 of them (EP300, TCF12, CTCF, POLR2A, CEBPB and NFIC) can act on four potential co-diagnostic genes simultaneously." (PMID 39744159, 2025).
epilepsy (1 paper, 2024). A brain disorder characterized by episodes of abnormally increased neuronal discharge resulting in transient episodes of sensory or motor neurological dysfunction, or psychic dysfunction. "Therefore, it is not possible to conclude epilepsy is a phenotypic feature of haploinsufficiency of TCF12." (PMID 39036055, 2024).
esophageal squamous cell carcinoma (1 paper, 2024). Esophageal squamous cell carcinoma (ESCC) is a type of esophageal carcinoma (EC) that can affect any part of the esophagus, but is usually located in the upper or middle third. "For example, circCRIM1 contributed to the development of esophageal squamous cell carcinoma by upregulating TCF12." (PMID 39469202, 2024).
Ewing sarcoma (1 paper, 2025). A small round cell tumor that lacks morphologic, immunohistochemical, and electron microscopic evidence of neuroectodermal differentiation. "Data 5), we selected six MTFs (TCF12, SOX6, POU3F1, POU3F2, NKX2-2, and IKZF2) as putative members of the Ewing sarcoma CRC, based on fulfilling at least two out of these three criteria." (PMID 41444391, 2025).
Facial palsy (1 paper, 2015). Facial nerve palsy is a dysfunction of cranial nerve VII (the facial nerve) that results in inability to control facial muscles on the affected side with weakness of the muscles of facial expression and eye closure. "This suggests that facial palsy or asymmetry could be a feature of TCF12 related conditions." (PMID 25871887, 2015).
female infertility (1 paper, 2025). Diminished or absent ability of a female to achieve conception. "Alteration within the dual allelic variants of transcription factor TCF12 causes female infertility; however, its impact on female reproduction is still unknown." (PMID 40754719, 2025). "The absence of Tcf12 in oocytes during the primordial follicular phase causes female sterility." (PMID 40754719, 2025).
folate deficiency (1 paper, 2025). A nutritional condition produced by a deficiency of FOLIC ACID in the diet. "Furthermore, after MTX, a folate antagonist, was used to cause folate deficiency, RT‒qPCR revealed that all these neurodevelopment-related genes were upregulated and reversed by folate supplementation, but except for Tcf12." (PMID 41266313, 2025).
gastric cancer (1 paper, 2021). A primary or metastatic malignant neoplasm involving the stomach. "Besides, some studies have found that overexpressing TCF12 upregulates p-AKT and p-PI3K and promotes gastric cancer (GC) development." (PMID 33413401, 2021).
glaucoma (1 paper, 2020). Increased pressure in the eyeball due to obstruction of the outflow of aqueous humor. "Finally, one mother who transmitted a splice acceptor variant (c.1189-2 A > G) in TCF12 was diagnosed with long QT syndrome and glaucoma (like the patient) but this shared feature is unlikely related to DD observed in the child or the variant in question." (PMID 33004838, 2020).
idiopathic pulmonary fibrosis (1 paper, 2024). Idiopathic pulmonary fibrosis (IPF) is a nonneoplastic pulmonary disease that is characterized by the formation of scar tissue within the lungs in the absence of any known cause. "Interestingly, we also have identified significant DEG-enrichments of target gene sets for five TFs, TCF12, ZEB1, NR3C1, TEAD4 and JUN, which were previously reported to be the regulators in idiopathic pulmonary fibrosis." (PMID 39103936, 2024).
liver cancer (1 paper, 2025). An epithelial or non-epithelial malignant neoplasm that arises from the liver. "Using bioinformatics analysis (n ═ 374 TCGA samples and n ═ 50 clinical specimens), we assessed TCF12 expression levels in liver cancer and evaluated their association with patient prognosis." (PMID 40190273, 2025). "In summary, this study demonstrates that TCF12 is highly expressed in liver cancer and is associated with poor prognosis." (PMID 40190273, 2025). "This study first identified, through database analysis, that TCF12 is highly expressed in liver cancer, and that high TCF12 expression levels are associated with poor prognosis in liver cancer patients." (PMID 40190273, 2025). "The prognostic significance of TCF12 in liver cancer was assessed using ROC analysis, yielding an AUC of 0.706." (PMID 40190273, 2025). "In liver cancer, TCF12 promotes lumen formation in vascular ECs by upregulating CXCR4 expression, which in turn enhances tumor cell migration and invasion, contributing to disease advancement." (PMID 40190273, 2025). "This trend was further confirmed in a cohort of 50 paired liver cancer and adjacent normal tissue samples, where TCF12 levels were also significantly elevated in cancerous tissues." (PMID 40190273, 2025). "The expression level of TCF12 in liver cancer was initially assessed using the TCGA database and Western blot analysis." (PMID 40190273, 2025). "It has been reported that TCF12 is involved in the occurrence and progression of various tumors; however, few studies have investigated its role in liver cancer angiogenesis and drug sensitivity." (PMID 40190273, 2025). "In conclusion, our study demonstrates that TCF12 promotes angiogenesis in liver cancer and influences the drug sensitivity of sorafenib." (PMID 40190273, 2025). "This study aims to assess TCF12 expression levels in liver cancer using data from the TCGA database and Western blotting, and to analyze the relationship between TCF12 expression and patient prognosis." (PMID 40190273, 2025). "Our bioinformatics analysis revealed that both TCF12 and HIF-1α are significantly overexpressed in liver cancer and are associated with poor prognosis." (PMID 40190273, 2025). "In summary, TCF12 promotes migration, tube formation, and permeability in liver cancer vascular ECs, suggesting it plays a key role in enhancing their angiogenic potential." (PMID 40190273, 2025). "In liver cancer specifically, TCF12 expression was significantly higher in 374 tumor samples compared to 50 normal liver tissues." (PMID 40190273, 2025). "TCF12 may represent a promising new target for liver cancer treatment and could provide insights into addressing sorafenib resistance." (PMID 40190273, 2025). "Additionally, immunohistochemical staining performed on two sets of liver cancer tissue microarrays demonstrated a positive correlation between TCF12 expression and CD31 levels." (PMID 40190273, 2025). "The results showed that TCF12 protein levels were significantly higher in liver cancer tissues." (PMID 40190273, 2025). "Furthermore, the analysis of TCF12 expression and prognosis in liver cancer patients suggests that those with high TCF12 levels have a worse prognosis." (PMID 40190273, 2025). "The expression of TCF12 in liver cancer tissues was examined via Western blotting and immunohistochemistry, while Kaplan-Meier survival analysis was used to analyze the relationship between TCF12 expression and overall survival." (PMID 40190273, 2025). "Moreover, reducing TCF12 expression increased the sensitivity of liver cancer cells to sorafenib." (PMID 40190273, 2025). "This study investigated the effects of TCF12 and HIF-1α on tube formation and drug sensitivity in liver cancer vascular ECs." (PMID 40190273, 2025). "TCF12 promotes angiogenesis by stabilizing HIF-1α and modulates tumor sensitivity to sorafenib, highlighting its potential as a therapeutic target in liver cancer." (PMID 40190273, 2025).